RN7SL375P (RNA, 7SL, cytoplasmic 375, pseudogene)
Gene: Miscellaneous RNA gene on chromosome 13 (60,034,465 to 60,034,762, reverse strand). Ensembl gene ENSG00000265745.
Homologues: Orthologues: chimpanzee Metazoa_SRP (99% identical), macaque Metazoa_SRP (94% identical). Paralogues in human: RN7SL3 (84% identical), RN7SL1 (84% identical), RN7SL2 (83% identical), RN7SL218P (80% identical), RN7SL228P (80% identical), RN7SL45P (80% identical), RN7SL732P (80% identical), RN7SL126P (80% identical), RN7SL296P (80% identical), RN7SL322P (80% identical), RN7SL448P (80% identical), RN7SL493P (80% identical), and 702 more.